YTHDF2 (YTH N6-methyladenosine RNA binding protein F2)
Diseases named in the same sentence as YTHDF2 in open-access papers (continued):
Sharing a sentence is not in itself a finding about the gene and the disease.
glioma (continued). "In gliomas, elevated YTHDF2 expression could suppress the expression of LXRα and HIVEP2 via m6A-dependent mRNA clearance, which is required for GSC growth, invasion, and tumor formation in vivo." (PMID 34246306, 2021). "Additionally, we identified UBXN1 as a prognostic factor for better survival of glioma patients with high YTHDF2 expression." (PMID 34246306, 2021). "Thus, in addition to GSCs, it is also necessary to study the role of YTHDF2 in differentiated glioma cells." (PMID 34246306, 2021). "Here, we show that YTHDF2 overexpression clinically correlates with poor glioma patient prognosis." (PMID 33420027, 2021). "Thus, we comprehensively investigated that expression level of YTHDF2 in gliomas with different histological grade, IDH-mutant status, WHO 2016 classifications, and primary/recurrent status in this study." (PMID 34246306, 2021). "Furthermore, we revealed that the expression of YTHDF2 significantly increased in recurrent gliomas compared with primary gliomas." (PMID 34246306, 2021). "Consistently, YTHDF2 has been reported to act as an oncogene in numerous tumors, including glioma." (PMID 34631793, 2021). "Next, we analyzed YTHDF2 protein levels in gliomas with different IDH status and WHO grades." (PMID 34246306, 2021). "Although this experiment was performed in human cervical cancer HeLa cells, unique regulation of separate mRNAs by YTHDF1 versus YTHDF2 in gliomas could provide an intriguing explanation for overexpression of both genes in high grade gliomas." (PMID 32375856, 2020). "In summary, miR-454-3p increased PTEN expression and reduced YTHDF2 expression in glioma cells." (PMID 33363140, 2020). "Considering these findings, a hypothesis was drew that EZH2 might participate in macrophage polarization in glioma via miR-454-3p/YTHDF2/PTEN axis." (PMID 33363140, 2020). "In addition, a prognostic model was constructed using the three genes (ZC3H13, HNRNPC, and YTHDF2) identified by LASSO regression, which stratified the OS of patients with gliomas into high- and low-risk groups." (PMID 33134160, 2020). "In the intricate network of glioma pathogenesis, the YTHDF family, consisting of YTHDF1, YTHDF2, and YTHDF3, and YTHDC1 and YTHDC2, as members of the YTH domain-containing family, play significant roles in the prognosis and molecular mechanisms underlying glioma." (PMID 38474421, 2024). "However, in glioma stem cells, YTHDF2 promotes glioma stemness by stabilizing MYC and VEGF mRNA." (PMID 38637831, 2024). "It’s becoming more and more clear that methylation regulators of the area of m6A in RNA, such as FTO and YTHDF2, may have an impact on glioma cell proliferation, carcinogenesis, proliferation and growth and invasion by influencing the levels of mRNA expression in their target genes." (PMID 37733705, 2023). "However, whether YTHDF2 can modulate NF-kB activation in gliomas through m6A modification remains unclear." (PMID 34246306, 2021). "Collectively, these results suggest that YTHDF2 might be involved in the malignancy of glioma." (PMID 33420027, 2021). "In our study, we confirm that PRMT6 promotes glioma cell migration, invasion, and EMT by transcriptionally activating YTHDF2." (PMID 38637831, 2024). "The related mechanism shows that in glioma, PRMT6 is recruited by the transcriptional regulator CDK9 to the YTHDF2 promoter region and then synergistically promotes the transcriptional activation of YTHDF2 with CDK9." (PMID 38637831, 2024). "In gliomas, the expression levels of METTL3, ALKBH5, YTHDF2, and IGF2BP3 were found to be elevated compared to normal brain tissues." (PMID 38398118, 2024). "For instance, YTHDF2 can promote the degradation of the UBXN1 gene, thereby influencing the NF-κB signaling pathway and promoting glioma progression." (PMID 38637831, 2024). "The results suggest that both PRMT6 and YTHDF2 can activate the Wnt-β-Catenin pathway, implicating its involvement in the regulation of glioma migration, invasion, and EMT by PRMT6 and YTHDF2." (PMID 38637831, 2024).
glioma (continued). "The expression of YTHDF2 was negatively correlated with CDKN2B and SPOCK2 mRNAs in multiple pediatric glioma datasets, supporting the pathological role of YTHDF2 negatively regulating CDKN2B and SPOCK2 transcripts in glioma development." (PMID 36973285, 2023). "A similar risk signature (ALKBH5, IGF2BP2, IGF2BP3, HNRNPA2B1, YTHDF1, YTHDF2, RBM15, and WTAP) was shown to be prognostic for glioma patients, and the expression of IGF2BP2 and IGF2BP3 was linked to tumour occurrence, development, and progression." (PMID 36831575, 2023). "YTHDF2 can activate NF-κB by accelerating the degradation of UBXN1 mRNA, thereby promoting glioma growth, proliferation, and metastasis." (PMID 37063421, 2023). "For instance, YTHDF2 facilitated m6A-dependent mRNA decay of LXRA and HIVEP2, which impacted the glioma patient survival." (PMID 37840133, 2023). "To examine the function of YTHDF2 in LGG, we used the qRT-PCR assay to detect the YTHDF2 expression in glioma cell lines." (PMID 35661004, 2022). "Previous studies have shown that YTHDF1, YTHDF2, IMP2 and hnRNPA2B1 are highly expressed in gliomas, while hnRNPC is poorly expressed in gliomas." (PMID 35688823, 2022). "Subsequently, the differential analysis showed that, between glioma and normal brain tissue, a variety of m6A-related genes were differentially expressed, including METTL14, METTL16, ZC3H13, YTHDC1, YTHDC2, YTHDF2 etc." (PMID 35559019, 2022). "To determine the expression of YTHDF2 in LGG, we adopt the public database to examine the expression of YTHDF2 in glioma tissues and normal group." (PMID 35661004, 2022). "Unlike METTL3, which only increases with grade in IDH-wildtype gliomas, we demonstrated that YTHDF2 increased along with increasing WHO grades in both IDH-mutant and IDH-wildtype gliomas." (PMID 34246306, 2021). "YTHDF2 expression was increased in primary gliomas with higher WHO grade and in IDH-wild-type gliomas in the Microarray cohort (n = 301) of CGGA." (PMID 34246306, 2021). "YTHDF2 facilitates m6A-dependent mRNA decay of LXRA and HIVEP2, which impacts the glioma patient survival." (PMID 33420027, 2021). "Consistent with our previous report, a recent study also showed that YTHDF2 expression is increased in GBM and has prognostic value in pan-gliomas." (PMID 34246306, 2021). "We found that ALKBH1, TRMT6, TRMT10C, YTHDF1, and YTHDF2 were significantly overexpressed in high-grade gliomas and the expression of TRMT6 and YTHDF2 was higher in IDH wild-type patients." (PMID 34631793, 2021). "In glioma research, a bioinformatics analysis in the CGGA microarray and RNA sequencing databases showed that the levels of YTHDC2, YTHDF1, YTHDF2, and YTHDF3 were elevated in gliomas." (PMID 34721530, 2021). "Here, we observed that YTHDF2 expression was also increased in GBM cell lines and differentiated tumor cells derived from GBM patient compared to human astrocytes and grade III glioma cell lines." (PMID 34246306, 2021). "Knockdown and overexpression were used to evaluate the effects of YTHDF2, methyltransferase-like 3 (METTL3), and UBX domain protein 1 (UBXN1) on glioma malignancy in cell and orthotopic xenograft models." (PMID 34246306, 2021). "RT-qPCR revealed that as the WHO grade of glioma increased, the expression of PTEN gradually decreased, while that of YTHDF2 gradually increased." (PMID 33363140, 2020). "There are several independent interaction groups in ‘readers’, suggesting the diverse functions of different ‘readers’, but the expressions of YTHDF2, YTHDC2 and YTHDF1 were significantly correlated with each other in gliomas." (PMID 30810537, 2019). "Individual m6A RNA methylation regulators, including METTL3, ALKBH5, YTHDF2, and IGF2BP3, have been assessed in patient datasets to examine their expression levels across normal tissues, lower-grade gliomas, and glioblastomas, as well as their prognostic significance." (PMID 38398118, 2024).
glioma (continued). "The findings suggest that the activation of the epidermal growth factor receptor (EGFR) contributes to YTHDF2 overexpression in glioblastoma, thereby linking EGFR signaling, a pivotal factor in the progression and resistance to therapy of glioma, to m6A-dependent mRNA modification." (PMID 38398118, 2024). "Additionally, positive correlations between the expression of YTHDF2 and immune checkpoints, including PD-1, TIM-3 and CTLA-4, have been observed in lower-grade glioma (LGG), emphasizing a role for YTHDF2 as a novel prognostic biomarker." (PMID 36810108, 2023). "Among the proteins with YTH domains, YTHDF1, YTHDF2, and YTHDF3 play pivotal roles in gliomas." (PMID 37964279, 2023). "Overall, the overexpression of YTHDF2 may simultaneously accelerate the degradation of UBXN1, LXRα, and HIVEP2 mRNAs, promoting glioma development through a complex network of actions." (PMID 35682599, 2022). "Moreover, YTHDF2 facilitates m6A-dependent mRNA decay of L-xylulose reductase (LXRA) and HIVEP zinc finger 2 (HIVEP2), which impacts the glioma patient survival." (PMID 35625706, 2022). "Taking all the previous results together, we found that high expression of YTHDF2 and TRMT6 is closely correlated with advanced WHO stage, IDH mutation, 1p19q non-codel, and poor clinical outcome in glioma." (PMID 34631793, 2021). "The specific biological functions and their mechanisms of YTHDF2 in glioma have not been reported until recently, mainly focusing on the studies of GSCs." (PMID 34246306, 2021). "Consequently, this study illustrated that EZH2 induced miR-454-3p DNA methylation by binding to miR-454-3p promoter to decrease miR-454-3p expression, thus upregulating YTHDF2 and m6A decoration of PTEN, which promoted M2 macrophage polarization in glioma." (PMID 33363140, 2020). "Moreover, the expressions of WTAP, RBM15, YTHDF2, YTHDF1 and ALKBH5 were highly correlated with each other, and all of their expressions were negatively correlated with FTO in gliomas." (PMID 30810537, 2019). "However, there are no reports yet on the impact of arginine methylation on YTHDF2 expression in glioma." (PMID 38637831, 2024). "The upregulated YTHDF2 binds to the mRNA of the negative regulatory factors APC and GSK3β in the Wnt-β-Catenin pathway that are modified by m6A, promoting their degradation and thereby activating the Wnt-β-Catenin pathway, ultimately promoting glioma migration, invasion, and EMT." (PMID 38637831, 2024). "Therefore, it is not surprising to find that YTHDF2 plays roles in cell proliferation of glioma cells." (PMID 38398118, 2024). "YTH n6-methyladenosine RNA binding protein 2 (YTHDF2) is downstream of epidermal growth factor receptor/src proto-oncogene, non-receptor tyrosine kinase/extracellular signal-regulated kinase (EGFR/SRC/ERK) and plays an important role in the proliferation and invasion of glioma cells." (PMID 35004688, 2021). "Thus, we next explore the correlation among miR-454-3p, YTHDF2, and PTEN in glioma." (PMID 33363140, 2020).
glioma (continued). "As is visible in the violin plot, the mRNA expression levels of YTHDF2, YTHDF1, METTL3, RBM15 and HNRNPC were up‐regulated in glioma compared to normal tissues, whereas the expression levels of ALKBH5, WTAP, YTHDC2, ZC3H13 and METTL14, especially of FTO, were decreased in glioma." (PMID 32449290, 2020). "Then, Pearson correlation analysis exhibited a negative correlation between YTHDF2 and PTEN expression and a negative correlation between miR-454-3p and YTHDF2 expression in the glioma tissue samples." (PMID 33363140, 2020). "As the co-IP results indicated, GBP2 could interact with KIF22 in glioma cells, but not DDX31 and YTHDF2." (PMID 35436989, 2022).
melanoma (52 papers, 2019 to 2025). A malignant, usually aggressive tumor composed of atypical, neoplastic melanocytes. "For instance, H3K18la promotes the progression of melanoma by facilitating the expression of the m6A reading protein YTHDF2." (PMID 41199784, 2025). "Conversely, the expression of YTHDF2 affects the sensitivity of melanoma cells to immunotherapy by regulating the level of PD‐1, an immune checkpoint protein." (PMID 38351531, 2024). "YTHDF2 promotes the degradation of PD‐1 mRNA, leading to lower PD‐1 protein expression on the surface of melanoma cells." (PMID 38351531, 2024). "Our findings revealed that the KO of Ythdf2 had minimal effects on B16 melanoma tumour growth in immunodeficient hosts, suggesting that the anti‐tumour effect of Ythdf2 KO is T‐cell‐dependent." (PMID 39568154, 2024). "Another study revealed that YTHDF2 was down-regulated as a tumor suppressor and inhibited melanoma tumorigenesis." (PMID 36870954, 2023). "In contrast, YTHDF2 was also found to be downregulated and served as a tumor suppressor in osteosarcoma and melanoma." (PMID 35382893, 2022). "claimed YTHDF2 can control melanoma metastasis by promoting NK cells to secret perforin, granzyme B, and IFN-γ in the tumour environment." (PMID 35572541, 2022). "It was also reported that high expression of YTHDF2 increased the decay of programmed death 1 (PD-1) mRNA, which played a significant role in melanoma." (PMID 35382893, 2022). "Other studies have shown that YTHDF2 is expressed at low levels in melanoma and osteosarcoma, where YTHDF2 can directly combine and accelerate the degradation of other oncogenes." (PMID 35382893, 2022). "In melanoma cells, YTHDF2 would serve as a tumor suppressor, mediating the downregulation of the FTO target genes." (PMID 34105069, 2021). "Of interest, the increased m6A methylation of important oncogenes in FTO knockdown cells also promoted YTHDF2-induced degradation in melanoma, whereas melanoma cells appear to be more sensitive to IFN-γ and enhance the efficacy of melanoma immunotherapy." (PMID 33692959, 2021). "A study showed that YTHDF2 can promote the degradation of PD1 mRNA in melanoma, and LHPP and NKX3-1 in prostate cancer." (PMID 34900689, 2021). "All tested MCC cell lines indicated higher expression level of YTHDF1 and YTHDF2 compared to the tested melanoma cell lines." (PMID 31947544, 2020). "m6A modification of the melanoma cell-intrinsic PD-1 (PDCD1) gene leads to increased mRNA decay via YTHDF2." (PMID 31239444, 2019). "YTHDF2 knockdown increases melanoma growth, whereas YTHDF2 overexpression decreases it, supporting a tumor suppressor role for YTHDF2 in melanoma." (PMID 31239444, 2019). "In melanoma, lactylation up-regulates YTHDF2, promoting mRNA decay of tumor suppressors." (PMID 40948941, 2025). "Additionally, p300 has been identified as a writer of H3K18la, which regulates YTHDF2 expression, facilitating melanoma progression." (PMID 40113760, 2025). "LncRNA JPX interacts with and destabilizes YTHDF2 to facilitate melanoma progression." (PMID 41145465, 2025). "The implicated mechanism involves the recognition of m6A-modified PER1 by the protein YTHDF2, which may accelerate melanoma progression." (PMID 40191195, 2025). "Targeting this lactate–lactylation–YTHDF2 axis may offer novel therapeutic avenues for metabolically active melanomas." (PMID 40948941, 2025). "YTHDF2 was identified to promote multiple melanoma cell proliferation via STAT5A/MAP2K2/p-ERK axis." (PMID 37256443, 2024). "Consistently, knockdown of YTHDF2 increased, while forced overexpression of YTHDF2 decreased, cell proliferation and migration in melanoma cells in vitro as well as tumor growth in vivo, supporting a tumor suppressor role for YTHDF2." (PMID 31239444, 2019). "As a result, YTHDF2 knockdown could increase the resistance of melanoma cells to immunotherapy." (PMID 38351531, 2024). "In addition, YTHDF2 could inhibit the progression of melanoma by suppressing the autophagy/NF-κB/FTO axis." (PMID 35382893, 2022).